MMP9 (matrix metallopeptidase 9)
Diseases named in the same sentence as MMP9 in open-access papers (continued):
Sharing a sentence is not in itself a finding about the gene and the disease.
myeloma (42 papers, 2000 to 2025). "Based on this, we will conduct a more comprehensive analysis and discussion on the exact roles of MMP-2 and MMP-9 in multiple myeloma, as well as their potential clinical implications." (PMID 37823051, 2023). "Consistently, heparanase, by enhancing MMP-9 expression, induces expression and shedding of Sdc-1 in myeloma and BC." (PMID 32604738, 2020). "One such target is MMP-9, which has been shown to control angiogenesis in multiple myeloma and is capable of driving the formation of metastatic niches in breast cancer." (PMID 32492898, 2020). "Studies have shown that the core protein of serglycin from myeloma cells can bind to proteases like MMP-9 (matrix metalloproteinase-9) and MMP-13." (PMID 29088739, 2017). "In multiple myeloma, a number of MMPs have been implicated in disease progression, most notably MMP-2 and MMP-9." (PMID 28241871, 2017). "We have previously shown that myeloma tumor burden is decreased in MMP-9 deficient mice, supporting a key role for host-derived MMP-9 in myeloma pathogenesis." (PMID 28241871, 2017). "For example, MMP-9 has been shown to control angiogenesis in multiple myeloma and genetic ablation of MMP-9 in an animal model can significantly delay the progression of the disease." (PMID 28611279, 2017). "Next, we examined the effects of tetrac and tetrac-NP on MMP-9 activity in primary cells from myeloma patients." (PMID 25071016, 2014). "In a parallel set of experiments, the inhibitory effect of tetrac on MMP-9 activity was observed under serum-containing conditions in various myeloma cell lines." (PMID 25071016, 2014). "In the current work we were have pursued the effects of the hormones on adhesion, migration and MMP-9 production—and possibly to block these actions—in myeloma cell lines as well as in primary bone marrow cells from myeloma patients." (PMID 25071016, 2014). "RGD peptide and tetrac impaired the production of MMP-9 in cell lines and in primary BM cells from myeloma patients." (PMID 25071016, 2014). "We demonstrated that thyroid hormones promote the adhesion of myeloma cells and that this interaction triggers clustering of αvβ3 integrin and the biosynthesis of the matrix degrading enzyme, MMP–9." (PMID 25071016, 2014). "To conclude, we have examined the role of thyroid hormones on multiple myeloma cell adhesion, migration and MMP-9 secretion." (PMID 25071016, 2014). "Disruption of the thyroid-integrin signaling by use of RGD or tetrac, a specific blocker of the thyroid hormone binding site upon the integrin, impaired the production of MMP-9 in myeloma cell lines and primary BM cells from myeloma patients." (PMID 25071016, 2014). "Serglycin synthesized and secreted by human acute monocytic leukemia cell line THP1 as well as serglycin isolated from myeloma cells forms complexes with proform of MMP9 (proMMP9) in vivo and in vitro." (PMID 24455486, 2014). "We present for the first time in myeloma cells that the inhibition by bortezomib of the secreted and activated form of MMP-9, an effect that is antagonized by T3 and T4." (PMID 25071016, 2014). "Furthermore, we quantitatively evaluated the mRNA expression of VEGF and MMP-9, which affects angiogenesis, using tumor tissues obtained from in vivo experiments in xenograft models using the multiple myeloma cell lines RPMI-8226 and IM-9." (PMID 35503759, 2022). "Thyroid hormone induces MMP-9 expression in myeloma cells that may contribute to myelomas migrating to bone locally." (PMID 34359854, 2021). "Furthermore, the ability of HPSE to stimulate the expression of MMP-9 through extracellular signal-regulated kinase phosphorylation in a myeloma setting demonstrated its regulatory role in promoting invasion." (PMID 33256730, 2020). "HPSE expression in myeloma cells enhances syndecan-1 shedding through activation of MMP-9." (PMID 33256730, 2020).
myeloma (continued). "In myeloma, re-expressing wild-type PTEN in PTEN-deficient cells represses proliferation and invasion by downregulating FAK, MMP2 and MMP9 expression and activity, indicating that HPSE and PTEN are targeting expression of the same proteins but in opposite ways." (PMID 32899927, 2020). "On the contrary, forced miR-29b expression inhibits osteoclast markers nuclear factor of activated T-cell, cytoplasmic 1 (NFATc1) and matrix metallopep (MMP9) expression and also reduces collagen degradation and pit formation of osteoclastic cultures in a multiple myeloma-mediated osteolysis model." (PMID 31627291, 2019). "Similarly, the fibronectin-assisted adhesion of EVs to myeloma cells stimulates the expression of MMP-9 in recipient cells, which promotes the myeloma progression." (PMID 30322133, 2018). "Combination of BMMPIs that target other MMP family members expressed in the bone microenvironment such as MMP-2 and MMP-9 therefore may act synergistically with bortezomib for the treatment of multiple myeloma." (PMID 28611279, 2017). "Indeed, host-derived MMP-9 has been shown to promote disease pathogenesis in a murine model of myeloma in vivo." (PMID 28241871, 2017). "The thyroid hormone-dependent regulation of MMP-9-integrin interactions defines a novel mechanism that may play a role in myeloma cell migration and disease progression." (PMID 25071016, 2014). "In conclusion, thyroid hormone-dependent regulation via αvβ3 of myeloma cell adhesion and MMP-9 production may play a role in myeloma migration and progression." (PMID 25071016, 2014). "A role for the αvβ3 integrin in the production of MMP-9 in myeloma has been reported." (PMID 25071016, 2014). "In this system, however, transfection of heparanase into myeloma cells, or addition of recombinant active heparanase enhanced their expression of pro MMP-9 in vitro and knockdown of heparanase expression in wt myeloma cells reduced the level of MMP-9 expression." (PMID 19360105, 2009). "Co-regulation of heparanase and MMP-9 expression was recently demonstrated in myeloma cells." (PMID 19360105, 2009). "Thus, osteoclasts not only support myeloma cell growth, but they also impede immune responses through several highly expressed negative regulators of immune response including, but not limited to, MMP9, MMP14, B7-H3, PD-L1, and PD-L2." (PMID 34150958, 2021). "Interestingly, SDF1α stimulates MMP-9 production in mouse myeloma model suggesting that SDF1α may have pleiotropic effects in both myeloma cell homing and invasion." (PMID 33634031, 2020). "Moreover, genetic ablation of MMP-9 results in a reduction in a myeloma murine model." (PMID 32492898, 2020). "Furthermore, the ability of roneparstat to inhibit multiple myeloma growth and angiogenesis has been correlated with disruption of the heparanase/syndecan-1 axis and downregulation of HGF, VEGF and MMP-9 gene expression controlled by endogenous heparanase in myeloma cells." (PMID 27374103, 2016). "Therefore, disruption of the thyroid hormones-integrin-MMP-9 signaling may be of importance in myeloma treatment." (PMID 25071016, 2014). "Increased HAT activity in Hpse-high myeloma cells resulted in upregulation of transcription of multiple genes (i.e., VEGF, HGF, MMP-9, RANKL) that drive an aggressive tumor phenotype." (PMID 36980232, 2023). "Similarly, EVs derived from aggressive myeloma patient cells, which bound to both RPMI-8226 plasmacytoma lymphocytes and human endothelial cells via surface-associated fibronectin, increased the expression of MMP-9 in the RPMI-8226 cells and promoted endothelial cell invasion." (PMID 36829629, 2023). "For example, in myeloma, HPSE drives aggressive tumour phenotype by up-regulating MMP-9 expression and activity within its TEM." (PMID 34677445, 2021). "This study generated a double deficient (RAG2–/–MMP-9–/–) mouse and demonstrated significant reductions of myeloma cells in the BM and OC number in the 5TGM1 bearing RAG2–/–MMP-9–/– mouse." (PMID 34163520, 2021).
myeloma (continued). "In summary, we can conclude that CSL not only inhibits migration and invasion of myeloma cells but also can downregulate the expression of CXCR4 and MMP-9 proteins in vitro." (PMID 29773987, 2018). "In situ hybridization analysis revealed that lymphoblastic leukemia B cells (SBcell line), multiple myeloma (MM) cells (U266 cell line) and lymphoblastic leukemia T cells(CEM and Jurkat cell lines) express constitutively the mRNA for MMP-2 and/or MMP-9." (PMID 11097203, 2000). "This review focuses on the role of MMP-1, MMP-2, MMP-7, MMP-9, MMP-13, MMP-14, and MMP-15 and the four types of TIMPs in the invasion of myeloma cells, angiogenesis, osteolytic osteopathy, to offer some novel perspectives on the clinical diagnostics and therapeutics of MM." (PMID 37823051, 2023). "Moreover, CSL can also inhibit the invasion and migration of cultured myeloma cells in vitro and downregulate the expression of CXCR4 and MMP-9 proteins." (PMID 29773987, 2018). "In contrast to our findings, a recent study by Raimondi and colleagues showed that exosomes derived from multiple myeloma cells increased osteoclastogenesis and expression of osteoclastic markers, including TRAP and MMP-9, in an in vitro system similar to ours, also using the RAW264.7 cell line." (PMID 27832183, 2016). "The activation of MMP-9 is not regulated by interleukin-6 (IL-6), the major myeloma cell growth factor, or by other cytokines involved in multiple myeloma." (PMID 25071016, 2014). "This drug, approved for the clinical treatment of patients with multiple myeloma and bone metastases, also inhibits BC growth, migration and invasion by targeting various ECM proteins, including integrins ανβ3, ανβ5, and α5β1, and Sdc-1, and by suppressing the expression of MMP-2 and MMP-9." (PMID 32604738, 2020). "In addition, another study on multiple myeloma patients revealed that MMP-2 and MMP-9 are secreted in higher amounts and are not balanced by inhibitors of TIMPs." (PMID 31474817, 2019).
brain injury (41 papers, 2010 to 2025). Acute and chronic (see also brain INJURIES, CHRONIC) injuries to the brain, including the cerebral hemispheres, CEREBELLUM, and brain STEM. "In this study, the post-traumatic mental disorder group exhibited higherserum MMP-9 levels compared to the simple brain trauma group, identifying MMP-9as a risk factor." (PMID 39801405, 2025). "A dual inhibitor of MMP-2 and MMP-9, known as SB-3CT, reduced brain lesion volumes and prevented neuronal loss and dendritic degeneration in an experimental mouse model of traumatic brain injury." (PMID 37109410, 2023). "Similar MMP-9 isoforms with variant pI values in the same molecular weight were also found in mouse brains after ischemic and traumatic brain injuries." (PMID 25859655, 2015). "Studies with 2D zymography further indicated changes in isoforms of MMP-9 with pI variants in neuroinflammation in microglial cells and in the models of acute brain injuries." (PMID 25859655, 2015). "The occurrence of post-traumaticmental disorder was taken as the dependent variable, while family satisfaction,the severity of traumatic brain injury, and serum levels of MMP-9,S100-β, and GFAP were included as independent variables." (PMID 39801405, 2025). "After ischemic brain injury, vascular endothelium impairment leads to release and activation of MMP-9." (PMID 36092813, 2022). "In conclusion, EK100 exerted the inhibitory actions on microglial JNK activation, and attenuated brain COX-2 expression, MMP-9 activation, and brain injuries in the mice ICH model." (PMID 34067678, 2021). "Treatment with IAIPs reduced myeloperoxidase (MPO) staining and co-localization of MPO and matrix metalloproteinase 9 (MMP9) in the brain of neonatal rats exposed to HI-related brain injury." (PMID 33276548, 2020). "It was widely accepted that iNOS and MMP9 play critical roles in damaging blood–brain barrier integrity and aggravating ischemic brain injury." (PMID 32317937, 2020). "In conclusion, our study explored the mechanism of ATP/P2X7R signaling in the disruption of BBB following brain trauma/stress injury, especially focusing on the relationship with IL-1β and MMP-9." (PMID 27795859, 2016). "IL-1β, one of the proinflammatory cytokines, is an important mediator of brain injuries/stress, and its role in the induction of MMP-9 has been well documented." (PMID 27795859, 2016). "MMP-9 can strongly degrade tight junction proteins and the basement membrane, thereby aggravating BBB damage and the propensity for HT that is associated with ischemic brain injury and thrombolytic therapy." (PMID 34162400, 2021). "Thus, our data support a protective PARP-dependent role of MMP-2 activity in hepatic IRI and are in line with the results of a recent study, which showed that PJ34 reduces MMP-9 and protects against traumatic brain injury." (PMID 26355684, 2015). "In this study, we suggested that BK-induced Nox2-mediated ROS signal, MMP-9 expression, and astrocytic migration might be involved in brain inflammation and remodeling during brain injuries." (PMID 23176293, 2012). "Among MMPs, MMP-9 expression and activation have been shown to be predominantly elevated by various brain injuries, suggesting that MMP-9 may be a critical molecule in the degradation of ECM and in the pathophysiology of many brain diseases." (PMID 21134288, 2010). "Thus, MMP-9 inhibition improved survival, liver functions, and brain injuries at the early stage." (PMID 36837539, 2023). "Matrix metalloproteinases-9 (MMP-9) have been found to play a critical role in BBB damage in various brain-related diseases, such as acute ischaemic stroke and traumatic brain injury." (PMID 40909460, 2025). "For example, PMNs release matrix metallopeptidase 9 (MMP-9) which degrades the BBB and exacerbates ischemic brain injury and tissue-plasminogen activator related hemorrhagic transformation." (PMID 31447626, 2019).
brain injury (continued). "In addition to serum MMP-9, S100-β, and GFAP, other biomarkers likeneuron-specific enolase (NSE) are also elevated after traumatic brain injury,reflecting the extent of neuronal damage." (PMID 39801405, 2025). "Secretion of MMP9 from microglia can be beneficial as well, contributing to ECM degradation around synaptic sites and promoting synapse reorganization and functional recovery following traumatic brain injury." (PMID 26441540, 2015). "In this clinical scenario but unfortunately not at the late stage, MMP-9 inhibition could improve survival, liver function, and brain injuries." (PMID 36837539, 2023). "Moreover, IL-1β-induced ROS signal and MMP-9 expression in brain astrocytes imply that IL-1β-mediated redox signals and MMP-9 induction may be vital for the development of brain injuries and inflammatory diseases." (PMID 35740292, 2022). "Therefore, the decrease in MMP-9 expression presently observed among asphyxiated newborns not developing brain injury may reflect an endogenous neuroprotective or neurorestorative mechanism or an effect of the hypothermia treatment." (PMID 25996847, 2015). "The relationship between severe traumatic brain injury (TBI) and blood levels of matrix metalloproteinase-9 (MMP-9) or cellular fibronectin (c-Fn) has never been reported." (PMID 23249478, 2012).
injury (40 papers, 2004 to 2025). Damage inflicted on the body as the direct or indirect result of an external force, with or without disruption of structural continuity. "MMP9 loss facilitated pulmonary cell death and aggravated lung injury in an interleukin-1β (IL-1β)-induced lung injury mouse model." (PMID 36387401, 2022). "In the present study, higher MMP-9 levels were associated with a higher prevalence of PTE after brain injury." (PMID 29667129, 2018). "MMP-7 and MMP-9 are known to cleave HS proteoglycans (including syndecan-1) and have been implicated in epithelial glycocalyx degradation in LPS- and bleomycin-induced lung injury." (PMID 34874923, 2022). "Therefore, the translational potential of MMP-9 after traumatic brain injury is promising in both the diagnostic and treatment domains." (PMID 33053032, 2020). "MMP-2 and/or MMP-9 have also been implicated in the development of experimental acute lung injury." (PMID 30616599, 2019). "In patients with craniocerebral trauma, serum levels of MMP-9, S100-β,and GFAP were found to be significantly altered." (PMID 39801405, 2025). "For example, Acupuncture bloodletting at the twelve Jing-well acupoints on the hands, reduces BBB permeability, and downregulates MMP9 expression in rats suffering from severe traumatic brain injury by inhibiting the MAPK signaling pathway." (PMID 41281566, 2025). "A 50% upregulation in MMP-9 level was observed in the TBI + Veh group compared to the sham group 24 h after brain injury (1.50 ± 0.02 vs. 1.0 ± 0.005, P < 0.001)." (PMID 37666857, 2023). "Macrophage-derived cytokines (ROS, IL) and inflammatory factors such as C-reactive protein (CRP), IL-6, IL-1 β, TNF- α and matrix metalloproteinase-9 (MMP9) after brain injury are related to renal injury." (PMID 35720359, 2022). "In traumatic brain injury, inhibition of Adam10 attenuated the upregulation of Mmp2 and Mmp9 expression." (PMID 35163191, 2022). "Consistently, the constructing PPI network in our result provides evidence that MAPK14 (p38α) activation was shown to make greater contributions to TLR4-mediated MMP-9-induced post-aSAH brain injury." (PMID 36438795, 2022). "Past studies have also linked induction of MMP2 and MMP9, and degradation of the ECM, to immune-mediated acute lung injury, and local MMP2 upregulation has been observed in experimental cerebral malaria." (PMID 33563839, 2021). "In acute lung injury, MMP-9 released from neutrophils will promote the inflammation and degradation of the alveolar capillary barrier, and further stimulate the migration and final structure of the alveoli." (PMID 34803696, 2021). "Compositional changes were associated with predominately M1-like macrophages, attenuated MMP9 release and decreased fibrogenesis in a model of bleomycin-induced lung injury." (PMID 34603325, 2021). "Brain injury increased active MMP-9 levels in the cerebral cortex and hippocampus within the first hour post-CCI." (PMID 29667129, 2018). "Male Nrf2 knock-out (Nrf2−/−) control mice had significantly higher HNE and NT levels, moreover in these mice the level of MMP-2 and MMP-9 significantly increased in cortical brain tissue lysate compared to wild-type (WT or Nrf2+/+) control animals in traumatic brain injury animal model." (PMID 33076449, 2020). "What’s more, inflammation-related factors including CRP, ICAM-2, and MMP-9 were also elevated, suggesting that after traumatic brain injury, the innate immune system was activated, then the inflammatory factors damaged the blood–brain barrier and were released into the blood." (PMID 30766469, 2018). "MMP-2 and MMP-9 are produced mainly by the microglia in a rat traumatic brain injury model." (PMID 25925889, 2015). "In the present study, KLK-5 expression was reduced in all asphyxiated newborns; KLK-5 promotes extracellular matrix degradation and neovascular sprouting by increasing MMP-9 activity, which, as previously noted, may contribute to brain injury." (PMID 25996847, 2015).